CD4 (CD4 molecule)
Diseases named in the same sentence as CD4 in open-access papers (continued):
Sharing a sentence is not in itself a finding about the gene and the disease.
autoimmune disease (continued). "To evaluate the potential impact of autoimmune disease on human naïve CD4+ T cell transcriptional heterogeneity, we analyzed filtered naïve CD4+ T cells from 4 adult (aSLE) and 27 pediatric (pSLE) lupus patients and matched healthy controls (5 aHD and 11 cHD)." (PMID 39866877, 2025). "CD4 + T-cells play a crucial role in the pathogenesis of autoimmune diseases." (PMID 40277886, 2025). "Therefore, in this study CD4(+) T cell immune profiling for an individual with compete monosomy X Turner syndrome (45, X), a female patient with GD (46, XX with autoimmune disease) and a healthy female (46, XX) was conducted." (PMID 39851522, 2025). "However, in various autoimmune diseases, the frequency and/or suppressive functions of peripheral CD4+CD25+FOXP3+ Tregs are abnormal." (PMID 40710338, 2025). "Tfh cells, categorized within the CD4+ T cell subset, essential for the formation of germinal centers, antibody maturation, and the maintenance of humoral memory in both autoimmune diseases and cancer settings, when they infiltrate, serve a protective role in breast and colorectal cancers." (PMID 40212965, 2025). "Therefore, CD4+ T cells are critical players in the pathology of infection, inflammatory and autoimmune diseases, and oncology." (PMID 40775564, 2025). "Additionally, CD4+ T cells bearing PD-1 accumulate at sites of inflammation in a variety of human autoimmune disorders, as evidenced by synovitis in rheumatoid arthritis and sialoadenitis in Sjogren's syndrome." (PMID 40158179, 2025). "Depletion of specific regulatory CD4+ T cell subsets could induce the spontaneous onset of various autoimmune diseases." (PMID 40757098, 2025). "The Th17 cells represent a major lineage of CD4+ T-cells that contribute to the maintenance of the first line of defense against pathogens at barrier surfaces, while conversely also playing a critical role in the development of autoimmune diseases." (PMID 40136531, 2025). "Whether similar changes in senescent CD4+ T cells occur in other autoimmune diseases remains to be determined." (PMID 41235706, 2025). "CD4+ T cells are central players in the pathogenesis of autoimmune diseases." (PMID 40001591, 2025). "CD4+ T cells are central mediators in specific autoimmune diseases." (PMID 41177827, 2025). "However, dysregulated CD4+ T cell responses can induce immunopathology, including autoimmune disorders." (PMID 41208998, 2025). "CD4+ T cells not only play a crucial supporting role in the activation of CTLs but also actively produce cytokines and chemokines, indirectly contributing to autoimmune diseases, asthma, allergic reactions, and tumor immunity." (PMID 38672418, 2024). "The differentiation of Th17 cells, a subset of CD4 + T cells that play an important role in combating extracellular microorganisms and autoimmune diseases in vivo, requires antigen presentation and costimulation, as well as the activation of antigen-presenting cells (APCs) to produce cytokines." (PMID 39622956, 2024). "On the basis of involvement of autoantibodies and human leukocyte antigen (HLA) class II in autoimmune diseases, CD4+ T cells are thought to be at the forefront of the pathogenesis of autoimmunity, and attempts have been made to elucidate their role in autoimmune diseases." (PMID 37788648, 2024). "MS patients treated with FTY showed the highest percentage of CD4+ T cells producing GRZB and the lowest percentage of CD4+ T cells producing IL-2, displaying a more cytotoxic profile, that is typically found in autoimmune diseases and, in particular, during MS." (PMID 38553477, 2024). "However, the true complexity of the roles of IL-17 expressing CD4 + T cells in human autoimmune disease, both in the blood and at local site of inflammation, are still being unraveled." (PMID 38431635, 2024).
autoimmune disease (continued). "DN T-cells with T helper (Th)-like properties are capable of secreting cytokines such as interleukin (IL)-4, IL-17, interferon-γ (IFN-γ), and tumor necrosis factor (TNF)-α, thereby assuming a role analogous to that of CD4 Th cells in cases of infection and autoimmune disease." (PMID 39544989, 2024). "CD4+ T cells are key mediators of various autoimmune diseases; however, their role in disease progression remains unclear due to cellular heterogeneity." (PMID 38359792, 2024). "Additionally, aryl hydrocarbon receptor regulates the differentiation and balance of CD4+ T helper 1, 2, 17, follicular, and regulatory immune cells, which are central in development of autoimmune diseases like SLE and DLE." (PMID 39552756, 2024). "Given that each autoimmune disease disorder possessed a characteristic CD4+ T cell profile, we hypothesized that disease status might be predicted solely from CD4+ T profiles by utilizing machine learning techniques and our autoimmune-wide scRNA-seq dataset." (PMID 38359792, 2024). "Murine models have shown that SD can influence the signaling of GM-CSF (Granulocyte-Macrophage Colony-Stimulating Factor) by regulating Th17 and activated CD4 T cells, which in turn interacts with myeloid cells, exacerbating the progression of autoimmune diseases." (PMID 38919616, 2024). "Foxp3+CD25+CD4+ natural regulatory T cells in dominant self-tolerance and autoimmune disease." (PMID 37469162, 2024). "Deletion of Tregs by thymectomy in 3-day-old mice and adult rats resulted in spontaneous multiorgan autoimmune diseases that could be prevented by the adoptive transfer of CD4+ T cells." (PMID 39000278, 2024). "This study suggests that Ts-Pmy may ameliorate CIA by restoring the immune balance of CD4+ T cells and provides new insights into the mechanism through which helminth-derived proteins exert their effects on autoimmune diseases." (PMID 38928413, 2024). "CD4+ T cells are considered the main orchestrators of autoimmune diseases." (PMID 39518908, 2024). "Sakaguchi and his colleagues made the discovery that the transplantation of CD4+ T cells might effectively reverse autoimmune disorders in mice that had their thymus removed." (PMID 39273452, 2024). "This flexibility is likely advantageous for sustaining the energy demands necessary for driving an autoimmune response, highlighting the adaptive capabilities of CD4+ T cells in the context of autoimmune diseases and contributing to their persistence and pathogenicity in conditions like uveitis." (PMID 39519064, 2024). "Different subtypes of Transitional B cells also have different functions, for example, the T2/T3 type produces IL-10 to reduce CD4+ T-cell proliferation but, in some autoimmune diseases, Trb also secretes anti-inflammatory factors (IL-6 and TNF-α) that disrupt the Treg/Th17 balance." (PMID 38812518, 2024). "Additionally, CD4+ T cells play an important role in the onset and progression of many autoimmune diseases, so we also examined the data in CD3+ CD4+ cells." (PMID 39595011, 2024). "Even the IFN-γ producing CD4+ T cell phenotype observed in the control group may possess anti-inflammatory properties, because this cytokine has pleiotropic properties in autoimmune diseases." (PMID 39769367, 2024). "Collectively, our analysis of these three autoimmune diseases suggests that the RI mechanisms observed in murine schistosomiasis may extend to human immunopathogenesis, highlighting the role of RI in CD4+ T cell-mediated diseases." (PMID 39661861, 2024). "To determine whether open chromatin in physical contact with dynamically regulated genes in CD4+ T cells is enriched for autoimmune disease heritability, we performed a partitioned LD score regression analysis." (PMID 39302339, 2024). "Numerous studies have shown that the variants on the HLA-DR binding groove could directly impact the binding affinity of exogenous antigens in presenting to CD4+ T cells and relate to autoimmune disease." (PMID 38540337, 2024).
autoimmune disease (continued). "In autoimmune disease, CD8 Treg may accumulate in the peripheral blood but fail to control the expansion of pathogenic CD4 T cells that subsequently cause tissue destruction." (PMID 39559361, 2024). "The predisposition of B6/Rab4AQ72L mice to MOG-induced EAE indicates that Rab4A activation may broadly enhance CD4+ T cell-dependent autoimmune diseases, including MS106." (PMID 38519468, 2024). "They express CD4 and the transcription factor forkhead box protein P3 (FoxP3) and play a crucial role in maintaining immune homeostasis by regulating peripheral tolerance and suppressing autoimmune diseases through diverse immunosuppressive mechanisms." (PMID 38894865, 2024). "Despite increased CD8 Treg numbers in populations with CD4-driven autoimmune diseases, the expansion of pathogenic CD4 T cells is not sufficiently inhibited to prevent pathology and/or disease progression." (PMID 39559361, 2024). "B cells are important effector cells that are involved in the pathogenesis of autoimmune diseases through the production of auto-antibodies, the promotion of CD4+ T cell responses via antigen presentation, and the release of inflammatory cytokines (e.g., TNF-α and IL-6)." (PMID 38339108, 2024). "Future research on the role of regulatory NK cells may help to fabricate and develop desirable therapeutic approaches to manage autoimmune diseases in a more targeted fashion, such as masking HLA-E on CD4+ T cells to kill activated autologous T cells." (PMID 37275764, 2023). "However, the effect of Mcl-1 inhibition in inducing cell death was most prominent in both CD4+/CD8+ T cells of healthy controls compared to autoimmune diseases." (PMID 37993903, 2023). "EAN was an autoimmune disease dominated by CD4+T cells and macrophage infiltration." (PMID 37217991, 2023). "The FoxP3 protein is the master regulator for development and function of CD4+CD25+CD127low Treg cells, where mutations of FoxP3 gene impair their development and function that may result in severe autoimmune disease." (PMID 37736101, 2023). "Interestingly, KDM6A is an X-linked gene that escapes X-chromosome inactivation in females, and KDM6A deletion in CD4+ T-helper cells resulted in autoimmunity amelioration in the context of multiple sclerosis, which is also a female-biased autoimmune disease." (PMID 38067106, 2023). "Moreover, targeting CD4 protein with monoclonal antibodies has shown promising results in T-cell-directed therapies, treating CD4-positive lymphomas, leukemias, and autoimmune diseases." (PMID 37736548, 2023). "The reasons for the female predilection for autoimmune disease remains unknown but is likely due to the genetics of the X chromosome, hormonal regulation of immune cells (CD4 T cells, monocytes, B cells and others) and the epigenetics affected by sex hormones." (PMID 37304263, 2023). "Moreover, CD4EM T cell expansion in patients with irAEs parallels CD4 memory abundance in classical autoimmune disease." (PMID 37794264, 2023). "Interleukin 2 (IL-2) is key in the activation of CD4 T-cells and regulates their homeostasis; it is also required for the activation in Treg cells therefore may play a role in autoimmune diseases." (PMID 37755547, 2023). "As CD40L is a co-stimulatory protein expressed by CD4+ T cells and the CD40–CD40L interaction is implicated in the pathogenesis of several diseases, this study contributes to our general understanding of autoimmune disease pathology." (PMID 37508433, 2023). "Memory-phenotype (MP) CD4+ T cells are a substantial population of conventional T cells that exist in steady-state mice, yet their immunological roles in autoimmune disease remain unclear." (PMID 37121980, 2023). "Furthermore, miR-125a-5p was identified as a commonly downregulated miRNA in CD4+ T cells of various autoimmune diseases, including Crohn’s disease, inflammatory bowel diseases, and SLE, indicating its potential negative regulatory role in inflammation." (PMID 37773129, 2023).
autoimmune disease (continued). "SLE is an autoimmune disease in which autoreactive CD4+ T cells play an essential role." (PMID 39872301, 2023). "However, many key questions about the potential contribution of memory CD4+ T cells to autoimmune disease remain unanswered." (PMID 36744136, 2023). "The IL-17A-expressing CD4 T cells are a key mediator of autoimmune diseases." (PMID 37175691, 2023). "Moreover, increased CD26+CD4+ T cells have been observed in subjects affected by immune-mediated disorders, including autoimmune diseases and graft-versus-host disease (GVHD)." (PMID 37170241, 2023). "Finally, all of our nine patients were found to share the same HLA haplotype region; HLA DRB1, DQA1, and DQB, which encode proteins that are found to play a key role in presenting antigens to CD4+ T cells in the autoimmune disease processes." (PMID 38259857, 2023). "An integrative analysis of CD4+ and CD8+ T cells from the multiple-autoimmune disease methylation, including Graves’ disease (GD), RA, SLE, and systemic sclerosis (SSc), demonstrated that hypomethylation of IFN-related genes is a common feature of autoimmune diseases in CD4+ T cells." (PMID 36609529, 2023). "Additionally, autoimmune diseases, malignancies, and acute and chronic viral infections make up the disorders in which CD4 CTLs play roles." (PMID 36737819, 2023). "According to our data, we suggest that there may be a positive feedback loop in CD4+ T cells regulating autoimmune disease." (PMID 39872301, 2023). "However, under the combination of certain genetic and environmental factors, inflammatory CD4+ T cells are known to accumulate abnormally, expediting the progression of autoimmune diseases." (PMID 36457711, 2022). "Previous studies have shown that abnormal metabolic reprogramming in CD4+ T cells could explain the occurrence of several autoimmune disorders, including Sjogren's syndrome (SS)." (PMID 35211629, 2022). "Furthermore, a correlation between the expression of OX40 on CD4+ T cells and disease severity has been observed in individuals with autoimmune diseases, such as SLE." (PMID 35265719, 2022). "Rheumatoid arthritis (RA) is an autoimmune disease affecting synovial joints where different CD4+ T cell subsets may contribute to pathology." (PMID 35831277, 2022). "Thus, the plethora of immature double-positive (CD4+/CD8+) self-reactive T-cells renders the patients with these types of tumors more vulnerable to the emergence of autoimmune diseases, especially MG." (PMID 35887212, 2022). "On the other hand, infusion of CD4+CD25+ T cells inhibited autoimmune disease development in mice." (PMID 36591309, 2022). "Currently, the prevailing theory is that TNFRSF9 agonists can be used to treat cancers and autoimmune diseases mainly mediated by CD4+ T cells, but may worsen autoimmune diseases mediated by CD8+ T cells." (PMID 35894206, 2022). "Since CD4 T-cell-specific PDPK1 deletion induces lymphoid atrophy, and PDPK1 deficiency in Treg cells generates severe spontaneous autoimmune diseases, which resemble the phenotypes observed in our KO and Treg-KO mice, we then examined PDPK1 and its downstream signaling molecules." (PMID 35210408, 2022). "IRF4 deletion in mice may induce transplant acceptance by establishing CD4+ T-cells dysfunction and render mice resistant to several autoimmune diseases, such as ulcerative colitis and experimental autoimmune encephalomyelitis." (PMID 36505471, 2022). "HIV positive individuals with weakened immune system (decreased CD4+ count) may develop opportunistic infections or autoimmune disease after immunity improves following combined antiretroviral therapy (cART)." (PMID 35382047, 2022). "IBD is an autoimmune disease involving autoantibodies and autoreactive CD4+ T lymphocytes." (PMID 35979355, 2022). "Dysregulation of the balance between subsets of CD4+ T cells, Tregs, and Th17 cells may be involved in the pathomechanism of several disorders, including autoimmune disease, cancer, and chronic inflammatory conditions." (PMID 35935991, 2022).
autoimmune disease (continued). "Th17 cells, a subset of CD4+T lymphocytes, produce inflammatory cytokines such as IL-6 and IL-17, which promote the body’s inflammatory response and are the main participants in autoimmune diseases." (PMID 36524110, 2022). "As polyclonal cells, iTreg can be massively expanded from naïve CD4+T cells in vitro, and it is easy to obtain the number of cells in therapeutic doses, suggesting that iTreg based therapy is a good choice for the treatment of autoimmune diseases." (PMID 35603221, 2022). "Based on human transcriptomic data, ANKRD55 is expressed in the ovaries, testes, endometrium, CD4+T cells, and monocytes, the latter two of which may be more important in autoimmune diseases." (PMID 35983018, 2022). "As with practically every cell-mediated immune response, CD4 CTLs may subserve potent protective immune responses against microbial pathogens as well as cancer and contribute to inflammatory and autoimmune diseases." (PMID 35572552, 2022). "A distinct CD4+ T‐cell phenotype is increased across multiple autoimmune disorders." (PMID 35119226, 2022). "Thus, a better understanding of the biological regulation of glutaminolysis in T cells, especially CD4+ T cells, will provide a new perspective for the treatment of autoimmune diseases." (PMID 36211442, 2022). "This suggested the importance of the inflammatory aspect of CD4+ T cells in autoimmune diseases." (PMID 35880181, 2022). "Targeted manipulation of TNFa-TNF receptor signaling on select CD4+ T cell subsets may offer specific therapeutic interventions to dampen inflammation while fortifying immune regulation for the treatment of autoimmune diseases." (PMID 36466853, 2022). "This study represents, to our knowledge, the first global methylation analysis that evaluates the temporal changes induced in circulating CD4+ T cells during pregnancy and how these changes relate to autoimmune diseases whose disease activity is altered during pregnancy." (PMID 34605719, 2022). "Our findings are consistent with observations from autoimmune disease models where FRCs indirectly restrain aberrant CD4+ T cell activation via MHCII presentation of self-antigen to induce proliferation of FoxP3+ Tregs and de novo conversion of Tregs in the mLNs under homeostatic conditions." (PMID 36227687, 2022). "IBD is an autoimmune disease involving both autoantibodies and autoreactive CD4+T lymphocytes." (PMID 35795556, 2022). "However, uveitis is a T cell-mediated autoimmune disease, and autoreactive CD4+T cells play a major role in the initiation and orchestration of EAU." (PMID 35401507, 2022). "Since the characteristics and the distribution of T lymphocyte subsets in autoimmune diseases are totally different from polymicrobial sepsis, the impacts of calcitriol on the polarization of CD4+ T cell subpopulations may differ." (PMID 36079813, 2022). "CD4 + T cells are essential in host defense, immunological modulation, and autoimmune disease." (PMID 35918384, 2022). "The autoimmune disease T1N is a well-characterised example, where hypothalamic cells that secrete hypocretin (a neuropeptide that stimulates wakefulness) are destroyed by auto-reactive CD4+ T-cells." (PMID 33558538, 2021). "However, the importance of DCs in priming self-reactive CD4+ T cells in autoimmune disease such as MS has been unclear." (PMID 33891644, 2021). "So, upregulated RN7SK RNA may cause disturbance in the P-TEFb complex with resulting regulation effects on CD4+ T cells, thus participating in autoimmune diseases such as idiopathic inflammatory myopathy (IIM) and MS." (PMID 34950142, 2021). "Additionally, increasing self-tolerance by promoting functional immunosuppressive CD4 T regulatory (Treg) cells is another alternative therapeutic for autoimmune disease." (PMID 34276700, 2021). "In addition to their critical role in defending against a wide array of invading microbes and pathogens, CD4+ T cells are key drivers of autoimmune diseases." (PMID 33598825, 2021).